SKP2 (S-phase kinase associated protein 2)
Diseases named in the same sentence as SKP2 in open-access papers (continued):
Sharing a sentence is not in itself a finding about the gene and the disease.
gastric adenocarcinoma (3 papers, 2021 to 2023). "Especially, SKP2 expression was positively correlated with Beclin-1 expression in gastric adenocarcinoma." (PMID 34414959, 2021). "The antioncogenic effect of Beclin-1 and FOXP3 expression in gastric adenocarcinoma is related to SKP2 expression." (PMID 34414959, 2021). "Our present results about SKP2 expression in gastric adenocarcinoma showed some different aspects compared with the results of previous studies." (PMID 34414959, 2021). "In conclusion, the antioncogenic effect of Beclin-1 and FOXP3 expression in gastric adenocarcinoma is corresponding to SKP2 expression." (PMID 34414959, 2021). "As a result, SKP2 overexpression in gastric adenocarcinomas showed a significant correlation with several favorable clinical factors, including the tumor size, T category, N category, lymphatic invasion, vascular invasion, OS, and DFS." (PMID 34414959, 2021). "Based on these findings, we can infer that the increased oncogenic properties of SKP2 in gastric adenocarcinoma are repressed by an increased FOXP3 expression." (PMID 34414959, 2021). "In our study, the SKP2 expression in gastric adenocarcinomas showed a significant correlation with favorable clinical factors, including the tumor size, T category, N category, stage group, recurrence rate, lymphatic invasion, vascular invasion, OS, and DFS." (PMID 34414959, 2021). "In addition, SKP2 expression was correlated with the tumoral FOXP3 expression in gastric adenocarcinoma." (PMID 34414959, 2021). "Therefore, we investigated why these results regarding SKP2 expression in gastric adenocarcinoma were obtained." (PMID 34414959, 2021). "Among the unknown effects of infiltrated Tregs on the prognosis of cancers, we have discovered that SKP2 expression is significantly related to Tregs in the tumor stroma of gastric adenocarcinoma." (PMID 34414959, 2021). "Moreover, the action of Tregs in tumor stroma is influenced by the tumor SKP2 expression in gastric adenocarcinoma." (PMID 34414959, 2021). "A positive SKP2 expression was observed in 47.8% (87/182) of the gastric adenocarcinoma samples." (PMID 34414959, 2021). "However, the function of SKP2 in gastric adenocarcinoma remains largely obscure." (PMID 34414959, 2021). "Correlation between SKP2 and tumoral FOXP3 expression and clinicopathological variables in 182 gastric adenocarcinomas." (PMID 34414959, 2021). "In the present study, the expression of SKP2 and its relationship with Beclin-1 and FOXP3 expression in gastric adenocarcinoma were investigated." (PMID 34414959, 2021). "Our study showed a complex interrelationship between SKP2 and Beclin-1 and FOXP3 expression in gastric adenocarcinoma." (PMID 34414959, 2021). "Our study showed a complex interrelationship among SKP2, Beclin-1, and FOXP3 expression (in the tumor cells and Tregs) in gastric adenocarcinoma." (PMID 34414959, 2021). "SKP2 expression was positively correlated with the tumoral FOXP3 overexpression (P < .0001), Beclin-1 expression (P < .0001), and Treg infiltration (P = .031) in gastric adenocarcinoma." (PMID 34414959, 2021). "Correlation among SKP2, tumoral FOXP3, Beclin-1, and Tregs in 182 gastric adenocarcinomas." (PMID 34414959, 2021).
glaucoma (3 papers, 2011 to 2013). Increased pressure in the eyeball due to obstruction of the outflow of aqueous humor. "Upregualtion of p27kip1 by transfection of skp2 siRNA can inhibit the proliferation of rabbit tennon’s fibroblast cells after glaucoma surgery which indicate it is important for inhibition of cell proliferation." (PMID 22419853, 2012). "We showed that expression of Skp2 can be detected in rabbit tenon’s fibroblast cells and confirmed that transfection of Skp2 siRNA can effectively inhibit the proliferation of rabbit tenon’s fibroblast cells after glaucoma surgery." (PMID 21270971, 2011).
Kaposi's sarcoma (3 papers, 2021 to 2023). A malignant neoplasm characterized by a vascular proliferation which usually contains blunt endothelial cells. "Soo Mi Lee in the Virology Program at Harvard Medical School, showed that cellular miR-127-3p suppresses KSHV-induced transformation and tumorigenesis via down-regulation of SKP2, identifying the miR-127-3p/SKP2 axis as a viable therapeutic avenue for Kaposi’s sarcoma." (PMID 37016725, 2023).
myxofibrosarcoma (3 papers, 2013 to 2023). A malignant fibroblastic neoplasm arising from the soft tissue. "ITGB2 participated in the YAP-induced cancer cell invasion by activating leukocyte-specific integrin β2 expression and the myxofibrosarcoma aggressiveness conferred by SKP2 amplification." (PMID 38022584, 2023). "The prognostic utility of p27 (Kip1) and its interacting cell cycle regulators in myxofibrosarcomas were analyzed: Skp2 overexpression is highly representative of the biological aggressiveness of myxofibrosarcomas and plays an important prognostic role." (PMID 24083250, 2013).
oral cancer (3 papers, 2015 to 2023). "A previous study showed that Skp2 overexpression was associated with tumor progression and poor prognosis in several tumors, such as ovarian, colorectal, gastric and oral cancer." (PMID 37779163, 2023).
prostate adenocarcinoma (3 papers, 2017 to 2026). "Within this group of genes, Ets2 (V-ets erythroblastosis virus E26 oncogene homolog 2) and Skp2 (S-phase kinase-associated protein 2, p45) were identified as proto-oncogenes, and Krt14 (Keratin 14) is a structural protein that is widely used as a marker for prostate adenocarcinoma." (PMID 28874141, 2017). "The vast majority of positive SKP2 staining are localized in nucleus and a few cores of prostate adenocarcinoma exhibit cytoplasmic staining." (PMID 41542047, 2026). "10% (1/10) of prostate normal tissue cores, 68.6% (33/49) of hyperplasia, 60% (3/5) of tumor adjacent tissues, 97.6% (41/42) of PIN, and 81% (113/138) prostate adenocarcinoma tissue cores were positive for SKP2." (PMID 41542047, 2026). "Also, the percentages of prostate hyperplasia, tumor adjacent tissues, PIN and prostate adenocarcinoma tissues that have SKP2 positive cells ranging from 68.6% to 97.6% are much higher than normal prostate tissues (10%)." (PMID 41542047, 2026). "SKP2 overexpression in mouse prostates induces atypical cell proliferation, leading to a progressive development of spontaneous prostatic lesions including hyperplasia, mPIN, and low-grade prostatic adenocarcinoma over 14 months of age." (PMID 41542047, 2026). "The densities of SKP2 positive cells progressively increase from normal prostate tissues to prostate hyperplasia, tumor adjacent tissues, PIN and prostate adenocarcinoma." (PMID 41542047, 2026). "Consistently with these results from the SKP2 humanized mouse, SKP2 protein is overexpressed in human prostatic hyperplasia, PIN and prostate adenocarcinoma compared to normal prostate tissues." (PMID 41542047, 2026). "IHC analysis reveals that SKP2 is sparsely overexpressed in prostate hyperplasia, tumor adjacent tissues, PIN and prostate adenocarcinoma compared to normal prostate tissues." (PMID 41542047, 2026).
Sepsis (3 papers, 2024 to 2025). Sepsis is defined as life-threatening organ dysfunction caused by a dysregulated host response to infection. "Taken together, these data indicate that Skp2 deficiency is responsible for inflammatory cytokine-induced ferroptosis in lung epithelial cells during sepsis." (PMID 39079969, 2024). "In this study, we found that the expression of S-phase kinase-associated protein 2 (Skp2) was significantly decreased in sepsis-induced acute lung injury (ALI)." (PMID 39079969, 2024). "Given the intricate mechanism underlying sepsis-induced death of pulmonary epithelial cells, we confirmed the specificity of decreased Skp2 expression in ferroptosis." (PMID 39079969, 2024). "Consistently, we confirmed the association between Skp2 depletion and the occurrence of sepsis in the present study, showing that the repression of Skp2 is implicated in the progression of sepsis through the regulation of ferroptosis." (PMID 39079969, 2024). "Based on the results of BALF, lung tissue, and pulmonary epithelial cell experiments, we found that Skp2 suppression during sepsis causes changes in the oxidative-reductive system in pulmonary epithelial cells, leading to ferroptosis." (PMID 39079969, 2024). "Through these experiments, we demonstrated the intricate association between Skp2 and ferroptosis in sepsis." (PMID 39079969, 2024). "However, sepsis-induced ALI aggravated by Skp2 deficiency was significantly attenuated by the administration of ferroptosis inhibitor Ferrostatin-1 (Fer-1)." (PMID 39079969, 2024). "In sepsis, inflammatory cytokine storms suppress Skp2 expression, leading to reduced SLC3A2 ubiquitination and disruption of the translocation of cysteine and glutamate." (PMID 39079969, 2024). "This suggests that HSPA8 downregulation plays a role by promoting the degradation of SKP2 in sepsis." (PMID 38698431, 2024). "Here, we aimed to investigate the impact of Skp2 on pulmonary epithelial ferroptosis and sepsis-induced ALI." (PMID 39079969, 2024). "In sepsis, suppression of the E3 ubiquitin ligase SKP2 activates the NLRP3 inflammasome by attenuating the level of ubiquitination modification of NLRP3." (PMID 38698431, 2024). "This suggests that the regulation of NLRP3 ubiquitination by SKP2 is involved in the process of lung injury in sepsis." (PMID 38698431, 2024). "Co-IP assay showed that there was a significant interaction between HSPA8 and SKP2 in sepsis." (PMID 38698431, 2024). "Together, these results suggest that inflammatory cytokines may be responsible for the decrease of Skp2 in sepsis." (PMID 39079969, 2024). "Skp2, which functions as an E3 ubiquitin ligase, exhibited noteworthy anti-inflammatory effects on ferroptosis triggered by inflammatory cytokines, and represents a promising approach for the management of sepsis-induced ALI." (PMID 39079969, 2024). "As reported in the literature, Skp2 was significantly inhibited during LPS-induced myocardial dysfunction, and the upregulation of circEXOC5 during acute lung injury accelerated Skp2 mRNA decay and aggravated sepsis-induced ALI." (PMID 39079969, 2024). "Therefore, the suppressed expression of Skp2 in sepsis patients hampered SLC3A2 ubiquitination and the translocation of cystine and glutamate, ultimately leading to ferroptosis." (PMID 39079969, 2024). "More importantly, we developed an efficient way to overexpress Skp2 in the lungs of mice and provided evidence that targeting Skp2 could be a potential strategy for treating sepsis-induced ALI through ferroptosis intervention." (PMID 39079969, 2024). "Notably, in our study, Skp2 heterozygous knockout mice displayed a more pronounced lung injury phenotype during sepsis than did wildtype mice." (PMID 39079969, 2024). "However, whether Skp2 plays a role in inducing ferroptosis during sepsis-induced ALI remains to be explored." (PMID 39079969, 2024).
Sepsis (continued). "Another study found that inhibiting Skp2 can promote ferroptosis by enhancing the ubiquitination of SLC3A2, thereby contributing to sepsis-induced acute lung injury." (PMID 40170095, 2025). "In present study, we showed that when HSPA8 protein levels in sepsis were knockdown by siRNA or inhibited by VER155008, SKP2 protein levels were subsequently reduced." (PMID 38698431, 2024). "In sepsis, HSPA8 interacts with the E3 ubiquitin ligase SKP2, and the down-regulation of HSPA8 promotes the degradation of SKP2." (PMID 38698431, 2024). "However, the regulatory mechanism of HSPA8 on SKP2 in sepsis-induced lung injury remains unclear." (PMID 38698431, 2024). "In this study, we show that SKP2, as an E3 ubiquitin ligase, its suppression attenuate NLRP3 protein ubiquitination and subsequently promote NLRP3 inflammasome activation in sepsis." (PMID 38698431, 2024). "Sepsis activated the MEK/ERK pathway and inhibited Skp2 expression in the pulmonary epithelium, resulting in a reduction of K48 ubiquitination of solute carrier family 3 member 2 (SLC3A2), thereby impairing its membrane localization and cystine/glutamate exchange function." (PMID 39079969, 2024). "This study aims at investigating the effect of HSPA8 signal activation in AECs on sepsis-induced lung injury, as well as exploring whether HSPA8 is involved in the regulation of E3 ubiquitin ligase SKP2 and NLRP3 inflammasome." (PMID 38698431, 2024). "In the present study, we utilized patient samples and a septic mouse model to investigate the impact of the absence of Skp2 on sepsis-induced acute lung injury (ALI) through the promotion of ferroptosis." (PMID 39079969, 2024). "Among all the Skp2-binding proteins, SLC3A2 (also known as CD98hc or 4F2hc), a cell-surface transmembrane protein that functions upstream of ferroptosis, decreased after the onset of sepsis, suggesting that the decrease in SLC3A2 during sepsis may be mediated by Skp2." (PMID 39079969, 2024). "The absence of Skp2 led to a significant increase in the protein concentration and total cell number in BALF, as well as a decrease in the wet/dry ratio, indicating that Skp2 deficiency exacerbated sepsis-induced ALI." (PMID 39079969, 2024). "In conclusion, the present study demonstrates that the suppression of HSPA8 promotes the degradation of SKP2, which in turn attenuates the ubiquitination and degradation of NLRP3 protein, leading to the activation of NLRP3 inflammasome and subsequent AECs pyroptosis in during sepsis." (PMID 38698431, 2024). "Despite the lack of direct evidence, there are hints suggesting that Skp2 might function as a protective protein in sepsis-induced ALI." (PMID 39079969, 2024). "However, it still not clear whether SKP2 is involved in the process of NLRP3 ubiquitination and what is the underlying mechanism for the alteration of SKP2 activity in sepsis-induced lung injury." (PMID 38698431, 2024).
uveal melanoma (3 papers, 2021 to 2023). A melanoma derived from melanocytes of the uveal tract. "Meanwhile, targeted inhibition of Skp2 has been proved to inhibit the progression of uveal melanoma by inhibiting the ubiquitination of P27." (PMID 35845132, 2022). "Skp2 is also abnormally expressed in uveal melanoma, and more and more effective treatments can be explored based on miR-590-5p and Skp2 in the future." (PMID 35845132, 2022). "Moreover, SKP2 expression was significantly correlated with poor PFI in individuals with KICH, LGG, LIHC, MESO, or UVM (uveal melanoma) (HR > 1, p < 0.05), as well as with considerable PFI in OV patients (HR < 1, p < 0.05)." (PMID 37308972, 2023).
autoimmune disease (2 papers, 2017 to 2019). A disorder resulting from loss of function or tissue destruction of an organ or multiple organs, arising from humoral or cellular immune responses of the individual to their own tissue constituents. "Additionally, other genes that were identified in our study, including BCL2, OAS1, MX1, and SKP2 have been previously associated with various autoimmune diseases." (PMID 29387060, 2017). "Moreover, Skp2 and p27 have been shown to function in autoimmune disease development." (PMID 31823770, 2019). "However, Skp2 affects cell cycle control and cell death, and its overexpression could decrease the suppressive effect of Tregs in the progression of autoimmune disorders." (PMID 31823770, 2019).
chronic kidney disease (2 papers, 2020 to 2024). Impairment of the renal function secondary to chronic kidney damage persisting for three or more months. "Calycosin suppresses autophagy and oxidative stress in chronic kidney disease skeletal muscle atrophy by regulating the AMPK/SKP2/CARM1 signaling pathway." (PMID 38650035, 2024).
Cirrhosis (2 papers, 2015 to 2023). A chronic disorder of the liver in which liver tissue becomes scarred and is partially replaced by regenerative nodules and fibrotic tissue resulting in loss of liver function. "Therefore, further investigation is required to elucidate the role of SKP2 in cirrhosis." (PMID 37679418, 2023). "On the other hand, the expression level of SKP2 showed a significant correlation with the cirrhosis history of HCC patients (p = 0.042), but not with their hepatitis history." (PMID 37679418, 2023).
colorectal tumors (2 papers, 2006 to 2011). "Colorectal tumours with high levels of CKS1 and SKP2 generally exhibit a more aggressive behaviour and are associated with low levels of CDKN1B (p27) and loss of tumor differentiation." (PMID 16919171, 2006).
endometrial cancer (2 papers, 2014 to 2022). Primary or metastatic malignant neoplasm involving the endometrium (mucous membrane that lines the endometrial cavity).
Ewing sarcoma (2 papers, 2013 to 2026). A small round cell tumor that lacks morphologic, immunohistochemical, and electron microscopic evidence of neuroectodermal differentiation. "For instance, in the context of Ewing sarcoma, it was previously demonstrated that EWS-FLI1 promotes the proteolysis of p27 protein via a Skp2-mediated mechanism." (PMID 23935076, 2013). "Among these, several necessary connections between ubiquitin proteasome system members (CUL1, SKP1, SKP2, ANAPC2) and EWS-FLI1 were identified, potentially indicating an interesting link between this oncogene and the protein turnover regulation in the context of Ewing sarcoma." (PMID 23935076, 2013).
Glucose intolerance (2 papers, 2016). Glucose intolerance (GI) can be defined as dysglycemia that comprises both prediabetes and diabetes. "For example, diminished β cell mass, hypoinsulinaemia and glucose intolerance occurred in Skp2(−/−) mice." (PMID 27349479, 2016). "As a result, Skp2-null mice have a decreased β-cell mass, hypoinsulinemia and glucose intolerance." (PMID 27380896, 2016).
head and neck carcinoma (2 papers, 2018 to 2020). A carcinoma that arises from the head and neck region. "Therefore, in the current study, we have elucidated the clinical relevance of curcumin for cancer treatment on a panel of human head and neck cancer cell lines by targeting deregulated overexpression of Skp2 and associated signaling components." (PMID 30333956, 2018). "Curcumin reduced cell viability and activated apoptosis by suppressing Skp2 in head and neck carcinoma." (PMID 32165861, 2020).
kidney cancer (2 papers, 2021 to 2023). Primary or metastatic malignant neoplasm involving the kidney. "S-phase kinase associated protein 2 (Skp2) is a member of the F-box family, which regulates the cell cycle and is highly expressed in various carcinomas, such as pancreatic, breast and kidney carcinoma." (PMID 33661942, 2021).
malignant pleural mesothelioma (2 papers, 2022). A malignant neoplasm that arises from mesothelial cells in the pleura and shows a diffuse growth pattern. "This was consistent with the reports that Skp2 drives the sensitivity to MLN4924 in malignant pleural mesothelioma and the sensitivity of RB cells to MLN4924 matches their dependency on Skp2." (PMID 35685435, 2022).